MYL7 (myosin light chain 7)
Synonyms: MYL2A; MYLC2A
Tractability: Small molecule: an approved drug acts on it.
Gene: Protein-coding gene on chromosome 7 (44,138,864 to 44,143,179, reverse strand). Ensembl gene ENSG00000106631.
Pathways (Reactome):
Muscle contraction: Smooth Muscle Contraction
Gene Ontology:
Molecular function: protein binding; calcium ion binding
Biological process: cardiac muscle tissue development; heart contraction
Cellular component: A band; cytoplasm; cytosol; myofibril; myosin complex; dendritic spine
Genetic constraint (gnomAD): Loss-of-function variants: 27 observed, 24.27 expected, observed/expected ratio (o/e) 1.11, 90% interval 0.82 to 1.53. The upper end of that interval is the gene's LOEUF score, 1.53, which puts it in group 6 of 6, group 1 being the genes least tolerant of losing a copy. Missense variants: 209 observed, 237.61 expected, observed/expected ratio (o/e) 0.88, 90% interval 0.79 to 0.99. Synonymous variants: 81 observed, 89.03 expected, observed/expected ratio (o/e) 0.91, 90% interval 0.76 to 1.09.
Homologues: Orthologues: chimpanzee MYL7 (100% identical), macaque MYL7 (99% identical), dog MYL7 (97% identical), mouse Myl7 (95% identical), rat Myl7 (95% identical), tropical clawed frog myl7 (75% identical), zebrafish myl7 (75% identical), Caenorhabditis elegans mlc-1 (42% identical), Caenorhabditis elegans mlc-2 (42% identical). Paralogues in human: MYL5 (62% identical), MYL10 (59% identical), MYL2 (59% identical), MYL11 (56% identical), MYL12A (49% identical), MYL12B (48% identical), MYL9 (47% identical).
Diseases named in the same sentence as MYL7 in open-access papers:
MYL7 is named in the same sentence as 17 diseases in open-access papers, as found by Europe PMC text mining. Sharing a sentence is not in itself a finding about the gene and the disease. The quoted sentences say what the papers report.
cardiac hypertrophy (7 papers, 2016 to 2025). "Mechanistically, we discovered that VASN deficiency downregulated MYL7 expression, which induced myocardial structure abnormalities and disorders, resulting in cardiac hypertrophy." (PMID 34854218, 2022). "Taken together, these findings show that VASN deficiency reduces MYL7 expression, which leads to cardiac hypertrophy (mechanism diagram)." (PMID 34854218, 2022). "Several genes, including NPPA (natriuretic peptide A), ACTC1 (alpha-cardiac actin), MYL2 (myosin regulatory light chain 2), and MYL7 (myosin regulatory light chain 7), have been previously implicated in cardiac hypertrophy." (PMID 34422789, 2021). "Our results revealed a pathological phenomenon in which VASN deficiency may lead to cardiac hypertrophy by downregulating MYL7 production." (PMID 34854218, 2022). "Our results reveal a pathological phenomenon in which VASN deficiency may lead to cardiac hypertrophy by downregulating MYL7 production." (PMID 34854218, 2022). "To further study the potential molecular mechanism by which VASN deficiency leads to cardiac hypertrophy, we studied whether changes in MYL7 expression affect myocardial fibre structure." (PMID 34854218, 2022). "Therefore, our results reveal a pathological phenomenon in which VASN deficiency may lead to cardiac hypertrophy by downregulating MYL7 expression." (PMID 34854218, 2022). "Myl7 has been shown to inhibit cardiac hypertrophy, whereas Wif1 impacts hypertrophy through inhibition of the Wnt/β-catenin pathway." (PMID 35380160, 2022). "The aim of this research was to ascertain whether VASN induces pathological cardiac hypertrophy by targeting myosin light chain 7 (MYL7)." (PMID 34854218, 2022). "Based on these studies, a novel pathological phenomenon was hypothesized in which VASN deletion leads to cardiac hypertrophy by affecting MYL7 expression." (PMID 34854218, 2022). "Compared to wild-type siblings, Tg(myl7:ATF3) zebrafish exhibited significant pathophysiological changes, including cardiac hypertrophy and features resembling hypertrophic cardiomyopathy." (PMID 41453996, 2025). "The greater degree of myl7 expression in the absence of an increase in pcna expression, together with the increase in cardiac muscle fibre cross-sectional area, suggests the presence of cardiac hypertrophy (muscle size) rather than hyperplasia (cell number)." (PMID 40682692, 2025).
heart failure (3 papers, 2019 to 2025). Inability of the heart to pump blood at an adequate rate to meet tissue metabolic requirements. "Tg(myl7:GA) larvae also revealed a decrease in time-averaged Ca2+ levels, but an increase in Ca2+ transient amplitude and stroke volume in a model of heart failure induced by terfenadine." (PMID 34680411, 2021). "The zebrafish line Tg(myl7:GA) allowed imaging both the time-averaged levels and the systolic Ca2+ transients continuously for several hours in control conditions, in response to drugs, and in a model of heart failure induced by terfenadine." (PMID 34680411, 2021). "Myl7 expression (an index of muscle mass and hypertrophy) in the heart was over 20% greater in KDs (p < 0.0001, n = 3), while nppa expression (activated in response to ventricular stress during hypertrophy and heart failure) was reduced by approximately 40% (p = 0.0012, n = 3)." (PMID 40682692, 2025).
diabetic cardiomyopathy (2 papers, 2016 to 2025). Diabetic cardiomyopathy is a disorder of the heart muscle in people with diabetes. "In addition, decreased expression of the genes playing a role in contractility including troponin I, myosin light chain 7 and myosin light chain kinase 2 could lead to sarcomeric dysfunction and diabetic cardiomyopathy." (PMID 27496100, 2016). "Sciatic nerve proteomics showed a significant increase in LRP group myosin, TNN13, MYL7, MYL3, TNNC, MYBPC2, ACTN2, and KEGG enrichment analyses showed that these proteins were mainly enriched in pathways such as cardiac contraction, diabetic cardiomyopathy, and dilated heart disease." (PMID 40321612, 2025).
Down syndrome (2 papers, 2013 to 2021). "Chimeric mice of chromosome 21, used as an animal model for Down’s syndrome, showed post-transcriptional down-regulation of endogenous Myl7, which was also seen in human patients." (PMID 22955375, 2013).
asthma (1 paper, 2023). "We identified two potentially novel (SETDB1 and ZNF8) and five previously reported (DM4C, DOCK8, MMP20, MYL7, and ADCY9) genes associated with increased asthma risk." (PMID 37569643, 2023).
Bradycardia (1 paper, 2021). A slower than normal heart rate (in adults, slower than 60 beats per minute). "Tg(myl7:GA) larvae treated with terfenadine showed bradycardia, 2:1 atrioventricular block, decreased time-averaged ventricular calcium levels but increased calcium transient amplitude, and reduced cardiac output." (PMID 34680411, 2021).
cardiomyopathy (1 paper, 2021). A disease of the heart muscle or myocardium proper. "Tg(myl7:Lifeact-GFP) transgenic zebrafish could be a useful model for future studies of cardiomyopathy from Smyd1 deficiency." (PMID 34765602, 2021). "In this study, we generated Tg(myl7:Lifeact-GFP) transgenic zebrafish models to study cardiomyopathy in smyd1b mutants and to investigate the effect of Lifeact-GFP overexpression on heart development." (PMID 34765602, 2021). "Together, these data indicate that Smyd1b is required for F-actin myofibril organization in cardiomyocyte, and Tg(myl7:Lifeact-GFP)mb21 transgenic zebrafish are a useful model to analyze F-actin myofibril defects in cardiomyopathy." (PMID 34765602, 2021). "In summary, our studies show that Tg(myl7:Lifeact-GFP) transgenic zebrafish is a useful model to study contractile dynamics of F-actin filaments in cardiomyocytes in vivo and to investigate cardiomyopathy from defective thin filament organization." (PMID 34765602, 2021). "In this study, we generated Tg(myl7:Lifeact-GFP) transgenic zebrafish models to investigate the effect of Lifeact-GFP expression on heart development and the use of Lifeact-GFP to study cardiomyopathy." (PMID 34765602, 2021).
COVID-19 (1 paper, 2023). A disease caused by infection with severe acute respiratory syndrome coronavirus 2. "Autoantibodies are more common in COVID-19 than controls and some (including against MYL7, UCH-L1, and GRIN3B) are more frequent with altered consciousness." (PMID 38135686, 2023).
dilated cardiomyopathy (1 paper, 2023). Cardiomyopathy which is characterized by dilation and contractile dysfunction of the left and right ventricles. "In the CardiacMeso-fated segment, Myl7 and Id2 were reduced relative to controls, as was Ankrd1, a gene implicated in sarcomere-binding and dilated cardiomyopathy that is known to be upregulated with overexpression of Mesp1." (PMID 36994838, 2023).
Fechtner Syndrome (1 paper, 2017). "Again, MYL7 mutations are associated with Fechtner Syndrome which features include hearing loss and eye abnormalities." (PMID 28993790, 2017).
hypertrophic cardiomyopathy (1 paper, 2025). A condition in which the myocardium is hypertrophied without an obvious cause. "The hearts of Tg(myl7:ATF3) zebrafish displayed a more compact and thickened ventricular wall compared to control WT zebrafish, resembling phenotypes associated with hypertrophic cardiomyopathy (HCM)." (PMID 41453996, 2025).
situs inversus (1 paper, 2023). A congenital condition in which there is complete right-to-left reversal of the position of the major thoracic and abdominal organs (that is, they are arranged in a mirror image of the normal positioning). "In particular, we found that heart looping in esrrγa morphants was significantly altered, as ∼20% of animals displayed either situs inversus or mid phenotypes of the heart marker myl7." (PMID 37232416, 2023).
cancer (1 paper, 2020). A tumor composed of atypical neoplastic, often pleomorphic cells that invade other tissues. "Transgenic fish that overexpresses ribose-5-phosphate isomerase A (RPIA) under the control of an intestinal fatty acid-binding protein (ifabp) promoter (Tg(ifabp:RPIA; myl7:EGFP) developed cancer in the gut at ~3 months of age." (PMID 32131390, 2020).
heart diseases (1 paper, 2017). "The MYL7 gene is also involved in regulating the actin cytoskeleton pathway, which is related to heart diseases." (PMID 28692647, 2017). "Some of those genes, including ITGA4, ITGB8, MYL7, ITGB7, HIF-1α and BNP, are assosiated with heart disease pathways and are recognized as myocardial injury biomarkers." (PMID 28692647, 2017).
MYL7 also shares sentences with these, for which no sentence is quoted: breast carcinoma (1 paper); cardiac septal defects (1); melanoma (1).